HP (haptoglobin)
Diseases named in the same sentence as HP in open-access papers (continued):
Sharing a sentence is not in itself a finding about the gene and the disease.
anemia (continued). "Further hematological tests including blood smear, reticulocyte count, hemolysis-related biochemistry (lactate dehydrogenase, bilirubin, and haptoglobin), and the direct antiglobulin test (DAT) should be performed to clarify the mechanism of anemia." (PMID 38577606, 2024). "This normocytic normochromic anemia is usually characterized by elevated indirect bilirubin, elevated LDH, decreased haptoglobin, increased reticulocyte count, and the presence of spherocytes in blood smear." (PMID 39839812, 2024). "Blood tests were sent, confirming anaemia, thrombocytopenia, AKI, and revealing an increase in LDH level, a reduction in C3 and haptoglobin level, and a normal value of C4 and ADAMTS13." (PMID 36977996, 2023). "The patient also presented with severe thrombocytopenia, anemia, with normal MCV, increased reticulocyte level, decreased haptoglobin, and increased lactate dehydrogenase (LDH) level, indicating hemolysis." (PMID 37046448, 2023). "The patient also presented with anemia, with slightly increased MCV, increased reticulocyte level, decreased haptoglobin, and increased lactate dehydrogenase (LDH) level, indicating hemolysis." (PMID 36750960, 2023). "Measuring haptoglobin levels, reticulocyte counts, elevated unconjugated bilirubin, and LDH can determine if hemolysis is present and to what degree, or if the anemia is primarily due to dapsone’s effect on folic acid metabolism." (PMID 37764145, 2023). "For example, anemia was present in only 68%, increased bilirubin in 58%, increased LDH in 42%, and decreased haptoglobin in only 37% of patients." (PMID 35681698, 2022). "Initial laboratory investigations on admission were significant for anemia, thrombocytopenia, high lactate dehydrogenase (LDH), low serum haptoglobin, and an increased reticulocyte count." (PMID 35812544, 2022). "Laboratory findings showed severe anemia with hemoglobin of 4.8 g/dl, platelet count of 48 x 10^3/mcL, elevated lactate dehydrogenase (LDH), decreased haptoglobin, and peripheral smear showing schistocytes." (PMID 34447649, 2021). "Suggestive features of CHAs are anemia and hemolysis, with high reticulocyte count, unconjugated hyperbilirubinemia, increased lactate dehydrogenase (LDH), and reduced haptoglobin." (PMID 34573891, 2021). "In all cases the records showed a detailed workup of all relevant differential diagnoses, including sepsis (microbiology workup) and evaluation of the anemia (Coombs test, LDH, haptoglobin, unconjugated bilirubin, schistocytes)." (PMID 31887162, 2019). "Autoimmune hemolytic anemia (AIHA): Direct antibody testing (Coombs) should be performed on all post-HCT patients with anemia, elevated LDH, and low haptoglobin." (PMID 31024873, 2019). "For those cases with available data at the time of grade 3 anaemia, we observed a wide range of haemolysis parameters, including bilirubin (0.4–2.0 mg/dL), LDH (165–560 units/L), haptoglobin (155–408 mg/dL), and reticulocytes (2.9–8.6%)." (PMID 30318513, 2018). "The diagnostic value of anemia, high LDH, low haptoglobin, and thrombocytopenia was not influenced by sex and age categories." (PMID 40630316, 2025). "In analyzing patients’ laboratory tests, we could frequently observe hemolysis markers such as anemia, elevated reticulocytes, elevated bilirubin levels, LDH, and low haptoglobin." (PMID 39766843, 2024). "The 4 Lab+ criteria included elevated LDH, low haptoglobin levels (in the absence of history of recent transfusion), dropping hematocrit/anemia/hemolytic anemia and thrombocytopenia." (PMID 37680648, 2023). "Workup revealed new onset of anemia (Hgb 10.5 g/dL), thrombocytopenia (platelets 23 × 109/L) with high lactate dehydrogenase (LDH 2,150 U/L), low haptoglobin 29 mg/dL, and new onset AKIN III, anuric renal failure (creatinine 4.63 mg/dL from baseline 1.3 mg/dL)." (PMID 36849497, 2023).
anemia (continued). "In addition, the potentially related diseases to specific patients’ proteins were anemias or hematopoietic system diseases (proteins HBZ, EPB41, HP, PGK1, HBE1, BPGM, and ALDOA)." (PMID 36519745, 2022). "Approximately 40% of the participants presented low haptoglobin levels regardless of anemia and sex classification." (PMID 35237470, 2022). "Initial workup revealed anemia, elevated lactate dehydrogenase (LDH), and low haptoglobin." (PMID 32509364, 2020). "Lactate dehydrogenase, haptoglobin, coagulation panel, fibrinogen, ADAMTS13 activity and inhibitor titer, complement, and urinalysis are recommended, along with the other common laboratory assessments for anemia." (PMID 32421502, 2020). "He experienced concomitant anemia and thrombocytopenia as well as elevated lactate dehydrogenase and low haptoglobin levels, but a TA-TMA diagnosis was not made due to an absence of schistocytes on peripheral smear." (PMID 29977661, 2018). "Haptoglobin levels increased over time in AI, suggesting that intravascular hemolysis does not contribute to the development of anemia during sepsis." (PMID 29717382, 2018). "Progressive anemia and thrombocytopenia instigated an evaluation for thrombotic microangiopathy, where confirmed by concomitant hemolysis, elevated lactate dehydrogenase (LDH), low haptoglobin, and concurrent oliguric acute kidney injury." (PMID 28774273, 2017). "In the presented case hemolysis parameters (haptoglobin and bilirubin) were normal and hence a combined anemia (hemolytic and IDA) was ruled out." (PMID 25514884, 2014). "In the expansion cohort at DL7, further grade 3 anemia events were observed, with some characterized by reactive reticulocytosis, increased bilirubin, and decreased haptoglobin in the absence of hemoglobinuria, in keeping with the extravascular hemolysis events noted preclinically." (PMID 33216844, 2020). "Microangiopathic hemolytic anemia is diagnosed when there are signs of anemia and hemolysis, such as schistocytes in a blood smear, increased lactate dehydrogenase, serum free hemoglobin, reticulocytosis, and diminished haptoglobin which may be a delicate, but nonspecific feature." (PMID 39087090, 2024). "Further workup of his anemia ruled out hemolysis, as he had a mildly elevated LDH and haptoglobin in the presence of a normal total bilirubin and ALT with no teardrop-shaped red blood cells on peripheral blood smear." (PMID 35280806, 2022). "First, the retrospective cohort did not include several anemia biomarkers, including circulating EPO levels, vitamin B12, serum folate and haptoglobin." (PMID 34831360, 2021). "TTP-HUS was suspected given the anemia, thrombocytopenia, elevated LDH activity, non-measurable haptoglobin, and the presence of schistocytes in the peripheral smear." (PMID 22206706, 2011). "Due to concomitant anemia and thrombocythemia (but no LDH elevation), screening for haptoglobin (elevated) and ADAMTS13 activity (elevated) was performed, and therefore, TTP and HUS could be ruled out." (PMID 40149624, 2025). "Likewise, the normal haptoglobin and LDH levels and negative Coombs test argue against ongoing hemolysis as a major contributor to the anemia." (PMID 40426810, 2025). "Even if we could not confirm the microangiopathic nature of anaemia until the third day in ICU, when peripheral smear finally confirmed the presence of schistocytes, the elevated LDH level and the decline in haptoglobin levels strongly suggested it from the beginning." (PMID 36977996, 2023). "Therefore, in our study only anemia and increased schistocyte counts stood out in the comparison of individuals with and without histologic evidence of TMA, since the groups were not different in terms of platelet counts, serum LDH, or haptoglobin levels." (PMID 33147224, 2020).
anemia (continued). "Laboratory findings at the University Hospital of Göttingen showed severe anemia (hemoglobin at 6 g/dL), thrombocytopenia (17.7 × 106 cells/μL), an increase in lactate dehydrogenase (LDH) activity (963 U/L, reference < 350 U/L), and negative haptoglobin (< 0.2 g/L, normal range 0.45 to 2.05 g/L)." (PMID 22206706, 2011).
Thrombocytopenia (82 papers, 2011 to 2026). A reduction in the number of circulating thrombocytes. "Yet, thrombocytopenia associated with undetectable haptoglobin can be seen in other setting than TMA (i.e. Cobalamin deficiency, Evans syndrome, hematoma resorption, intramedullary hemolysis, paroxystic nocturnal hematuria, malaria, hepatic failure...)." (PMID 34797873, 2021). "Laboratory evaluation demonstrated hemolytic anemia with marked reticulocytosis, thrombocytopenia, elevated lactate dehydrogenase, low haptoglobin, and indirect hyperbilirubinemia." (PMID 42291848, 2026). "On day 15, diagnostic criteria for HUS were fully met: MAHA (low hemoglobin, high LDH, low haptoglobin, schistocytes >1%), thrombocytopenia, and normal ADAMTS13 (96.45%)." (PMID 41383869, 2025). "Laboratory investigations showed hemoglobin of 5.8 g/dL, 3.5% schistocytes, undetectable haptoglobin, and severe thrombocytopenia (20,000/mm3), consistent with thrombotic microangiopathy (TMA)." (PMID 41158850, 2025). "Patients had de novo prolonged or progressive thrombocytopenia (6/14, 43%), decreased hemoglobin concentration (4/14, 29%), reduced serum haptoglobin level (3/14, 21%), and a sudden and persistent increase in lactate dehydrogenase level (2/14, 14%)." (PMID 38649868, 2024). "He had severe hemolytic anemia (hemoglobin (Hb) 4.9 (13.6–16.6 g/dL)) with schistocytes on the peripheral blood film, low haptoglobin, raised lactate dehydrogenase levels, and thrombocytopenia." (PMID 36298637, 2022). "During the period mentioned earlier, we identified 427 patients with thrombocytopenia and schistocytosis ≥0.5% and 4,664 patients with haptoglobin ≤0.4 g/L." (PMID 33718396, 2021). "Laboratory results revealed hemolytic anemia (Hb = 9.8 g/dL, haptoglobin < 0.1 g/L and schistocytes) and thrombocytopenia (platelet count 99 G/L)." (PMID 32000700, 2020). "Our patient was also found to have hemolytic anemia, schistocytes on peripheral smear, thrombocytopenia, acute kidney injury, low haptoglobin levels, low C3, C4, CH-50 levels, and normal ADAMTS 13 levels, all of which suggestive of HUS." (PMID 31010328, 2019). "Consumption and hemolysis of erythrocytes, followed by a low leucocyte count and thrombocytopenia, was seen in two patients (Pt8, and Pt9); haptoglobin and carboxyhemoglobin (CoHb) were below the detection limit." (PMID 28592808, 2017). "Multiple peripheral blood films, serum haptoglobin levels, and reticulocyte counts were found normal, except for thrombocytopenia, since detection of thrombocytopenia." (PMID 27495036, 2016). "As shown in the case presentation, the initial laboratory abnormalities included hemolysis (elevated bilirubin predominantly indirect type, elevated LDH, decreased haptoglobin, and elevated immature reticulocyte fraction), transaminitis, and severe thrombocytopenia." (PMID 40630741, 2025). "In conclusion, our review supports the view that iTTP may be a rare complication in IIM, which clinicians should consider in cases of marked thrombocytopenia despite normal haptoglobin concentrations." (PMID 36576539, 2023). "The patient presented with leukopenia (white blood cell count 3,900/μL), haemolytic anaemia (haemoglobin 9.7 g/dL, haematocrit 29.2 %, and haptoglobin < 10 mg/dL), thrombocytopaenia (platelet 41,000/μL), and azotaemia (blood urea nitrogen 52.9 mg/dL and serum creatinine 2.8 mg/dL)." (PMID 33691638, 2021). "After 32 cycles, there was complete resolution of haemolytic anaemia (haemoglobin 13.7 g/dL, haematocrit 41.8 %, and haptoglobin 119 mg/dL), thrombocytopaenia (platelet count 149,000/μL), and azotaemia (blood urea nitrogen 13.0 mg/dL, serum creatinine 1.10 mg/dL)." (PMID 33691638, 2021). "Two patients developed clinical features consistent with a microangiopathic hemolytic anemia (MAHA) syndrome with proteinuria, hemolytic anemia, low haptoglobin, thrombocytopenia, and serum creatinine increase, 4 weeks after pazopanib initiation and 2 weeks after the first bevacizumab infusion." (PMID 28810837, 2017).
Thrombocytopenia (continued). "He had a severe hypoproliferative megaloblastic anemia with hemolysis (hemoglobin 61g/L, mean corpuscular volume 99fL, reticulocytes 0.8%, haptoglobin undetectable), leukopenia (2.7×109/L), thrombocytopenia (96×109/L), ataxia with central demyelination, and megaloblastic madness." (PMID 25128288, 2014). "How the implementation of health electronic records’ red flags, or systematic schistocytes count and haptoglobin measurement, could improve the early diagnosis of iTTP among patients presenting to the ER with severe thrombocytopenia deserves to be investigated." (PMID 34797873, 2021). "Hematologic evaluation revealed thrombocytopenia (platelet count: 94,000/mm3) and MAHA, with a hemoglobin level of 6.7 g/dL, LDH of 1142 U/L, and undetectable haptoglobin (<5 mg/dL)." (PMID 40422585, 2025). "Patients often present with hemolytic anemia, thrombocytopenia, elevated LDH and bilirubin, low haptoglobin, and schistocytes." (PMID 39967609, 2025). "The clinical presentation of TMA was clear, with the presence of schistocytes on the peripheral smear, elevated LDH, and low haptoglobin indicating hemolysis, along with AKI and thrombocytopenia." (PMID 39583481, 2024). "Our patient presented with thrombocytopenia, AKI, and hemolytic anemia (elevated LDH and low haptoglobin levels), suggesting TTP, aHUS, or TMA." (PMID 37832064, 2023). "In both analyzed cases, we observed a very high degree of thrombocytopenia, high levels of d-dimers, markers of increased hemolysis—high LDH, low haptoglobin, a decrease in hemoglobin, and a moderate increase in creatinine levels." (PMID 36141710, 2022). "Microangiopathic hemolytic anemia (reduced Hb and haptoglobin, increased LDH and presence of schistocytes) and thrombocytopenia are sufficient for presumptive diagnosis of TTP." (PMID 35891176, 2022). "Thrombocytopenia in the presence of schistocytes, elevated LDH and total bilirubin, decreased haptoglobin, and hemoglobinuria, are useful laboratory markers to identify a thrombotic process with microvascular destruction of erythrocytes." (PMID 25429351, 2014). "Laboratory evaluation revealed severe macrocytic anemia (hemoglobin 3.5 g/dL, mean corpuscular volume (MCV) 136.9 fL) with thrombocytopenia, elevated lactate dehydrogenase (LDH) (2905 U/L), indirect hyperbilirubinemia, and suppressed haptoglobin, findings suggestive of hemolysis." (PMID 41717155, 2026). "High LDH, MAHA, thrombocytopenia, schistocytes in peripheral blood smear, low haptoglobin, negative direct Coombs test, high indirect bilirubin." (PMID 39918340, 2025). "All patients showed laboratory manifestations of MAHA including low Hb, PB, schistocytes >2%, increased reticulocytes, reduced haptoglobin, increased LDH, and thrombocytopenia, in addition to impaired renal function tests, and all of them had normal ADAMTS13 levels." (PMID 34840826, 2021). "She presented thrombocytopenia (67G/L) and mechanical hemolytic anemia: haemoglobin = 7.9 g/dL, reticulocyte = 175G/L, presence of schistocytes, Lactate Dehydrogenase (LDH) = 1058 UI/L and haptoglobin < 0.1 g/L." (PMID 32000700, 2020). "The diagnosis of thrombotic microangiopathies, including TTP, requires the presence of thrombocytopenia with nonimmune microangiopathic haemolytic anaemia (schistocytes found as erythrocytes fragments, reduced haptoglobin concentration, elevated reticulocyte count, LDH, and indirect bilirubin)." (PMID 40217615, 2025). "TMA: microangiopathic hemolytic anemia (high LDH serum levels, low haptoglobin, presence of schistocytes in peripheral blood smear, negative Coombs test).Thrombocytopenia.Other organs could be affected: central nervous system." (PMID 40115110, 2025). "In sum, there were no diagnostic clues for classic TMA (lacking schistocytes, normal or elevated haptoglobin levels, no severe thrombocytopenia) in any of our patients whereas the consistently high VWF levels were compatible with an endothelial activation and/or damage." (PMID 33572417, 2021).
Thrombocytopenia (continued). "However, the development of acute microangiopathic hemolytic anemia (that is, low haptoglobin, elevated LDH, and schistocytes in the peripheral smear), acute encephalopathy, thrombocytopenia, and low serum ADAMTS 13 activity were enough evidence to suspect TTP and to start plasmapheresis." (PMID 31228952, 2019). "However, in the absence of peripheral schistocytes, thrombocytopenia, decreased plasma haptoglobin, absence of thrombi in the biopsy, and normal serum trough tacrolimus levels, tacrolimus-induced HUS leading to elevated LDH was unlikely 17 years after the transplantation." (PMID 39597031, 2024). "She had severe macrocytic anemia (Hb 5.8 [11.8–14.6 g/dL]); thrombocytopenia (Plt 7 [150–360 × 109/L]); conjugated hyperbilirubinemia, raised reticulocyte counts and LDH, low haptoglobin, hypocomplementemia, and mildly raised troponin I. No schistocytes were seen on the peripheral blood film." (PMID 36298637, 2022). "Features of TA-TMA include microangiopathic, Coombs-negative haemolytic anaemia and thrombocytopaenia, high serum lactate dehydrogenase (LDH) levels, decreased or undetectable haptoglobin levels, schistocytosis on peripheral blood smear, target organ damage and transfusion requirements." (PMID 28993886, 2018).